ENSG00000273259 (novel protein)
Gene: Protein-coding gene on chromosome 14 (94,592,058 to 94,624,646, forward strand). Ensembl gene ENSG00000273259.
Genetic constraint (gnomAD): Missense variants: 37 observed, 37.39 expected, observed/expected ratio (o/e) 0.99, 90% interval 0.76 to 1.3. Synonymous variants: 17 observed, 14.96 expected, observed/expected ratio (o/e) 1.14, 90% interval 0.78 to 1.68.